FOXD4L6 (forkhead box D4 like 6)
Synonyms: OTTHUMG00000066822
Tractability: No criterion of Open Targets' tractability assessment is met for any kind of drug.
Gene: Protein-coding gene on chromosome 9 (41,126,435 to 41,128,681, reverse strand). Ensembl gene ENSG00000273514.
Subcellular location: Nucleus
Subcellular location (Human Protein Atlas): Nucleoplasm
Gene Ontology:
Molecular function: protein binding; DNA-binding transcription factor activity, RNA polymerase II-specific; RNA polymerase II cis-regulatory region sequence-specific DNA binding; DNA-binding transcription factor activity; sequence-specific DNA binding
Biological process: anatomical structure morphogenesis; cell differentiation; regulation of transcription by RNA polymerase II; regulation of DNA-templated transcription
Cellular component: chromatin; nucleus
Genetic constraint (gnomAD): Loss-of-function variants: 1 observed, 3.12 expected, observed/expected ratio (o/e) 0.32, 90% interval 0.11 to 1.43. That is too few expected variants to judge how well the gene tolerates losing a copy. Missense variants: 21 observed, 111.83 expected, observed/expected ratio (o/e) 0.19, 90% interval 0.13 to 0.27. Synonymous variants: 9 observed, 46.5 expected, observed/expected ratio (o/e) 0.19, 90% interval 0.12 to 0.34.
Homologues: Orthologues: mouse Foxd4 (50% identical). Paralogues in human: FOXD4L3 (99% identical), FOXD4L4 (98% identical), FOXD4L5 (98% identical), FOXD4 (85% identical), FOXD4L1 (71% identical), FOXD1 (33% identical), FOXD2 (31% identical), FOXD3 (30% identical), FOXE3 (25% identical), FOXC1 (23% identical), FOXC2 (23% identical), FOXE1 (23% identical), and 29 more.